IL6 (interleukin 6)
Diseases named in the same sentence as IL6 in open-access papers (continued):
Sharing a sentence is not in itself a finding about the gene and the disease.
endotoxemia (continued). "We further demonstrated that ATF3 gene knockout in mice subjected to LPS-induced endotoxemia correlates with an increase in the mortality rate and the elevated expression of IL-6, TNF-α, NO, MCP-1, and HMGB1 in the lung tissues or serum." (PMID 24062788, 2013). "(BxS)F1 females also suffered less from LPS-induced hypothermia and produced less IL6 (p = 0.0014) and other cytokines and chemokines than (BxS)F1 males, which indicates that they are less sensitive to acute endotoxemia." (PMID 23495141, 2013). "In contrast, the immunoneutralization of IL-10 led to elevated levels of circulating TNF-α and IL-6 in mice and reversed the ability of IL-10 to protect mice from lethal endotoxemia." (PMID 23853427, 2013). "The serum levels of IL-6, IL-8, and IL-18, were reported to be increased secondary to systemic endotoxemia, in patients with alcoholic liver disease and steatohepatitis." (PMID 23097664, 2012). "Apart from the inhibition of serum TNF-α during endotoxemia, T-5224 decreased other serum cytokines, namely IL-1β and IL-6." (PMID 23173923, 2012). "Recently developed novel cytokine antagonist therapies targeting TNF-α and IL-6 have been found to be quite effective in certain types of endotoxemia." (PMID 22114683, 2011). "Continuous intravenous administration of adenosine attenuated the IL-6 response during human endotoxemia." (PMID 22129171, 2011). "Unlike other pro-inflammatory cytokines, HMGB1 is a "late-appearing" inflammatory mediator, because its release during endotoxemia is delayed in comparison with the rapid increase of early pro-inflammatory cytokines such as IL-1β, IL-6 and TNF-α." (PMID 19799777, 2009). "It is postulated that bacterial lipopolysaccharide (LPS) stimulates IL-6 production and thus up-regulates hepcidin release leading to hypoferremia, as reported in human endotoxemia models." (PMID 19107209, 2008). "Genetically modified mice expressing low levels of F3 exhibited reduced IL-6 expression and increased survival during endotoxemia." (PMID 17450221, 2007). "A recent human experimental endotoxemia model showed that peak interleukin-6 (IL-6) levels were reduced by half in volunteers treated with CytoSorb 15 min after the start of a 3-h lipopolysaccharide challenge, but most controlled clinical studies have been negative." (PMID 41140657, 2025). "Furthermore, IL-6 demonstrates protective effects against LPS-induced endotoxemia by increasing the production of IL-10 and modulating cytokine responses, which includes the enhancement of hepatic antioxidant enzymes." (PMID 40564288, 2025). "Recently, in an endotoxemia model, IL-6 plasma clearance significantly decreased over time, decreasing from 25 mL/min (approx. equivalent to 20% extraction ratio at 250 mL/min blood flow) to 10–15 mL/min (approximately 9% extraction ratio) after 5–6 h of treatment with CytoSorb." (PMID 41140657, 2025). "MV with endotoxemia increased microvascular permeability, lung edema, interleukin-6 and metalloproteinase-9 production, oxidative loads, ER stress biomarkers (GRP78, IRE-1α, PERK), morphological rearrangement, PI3K-γ expression, and bronchial epithelial apoptosis in rodent lungs." (PMID 40565223, 2025). "Altogether, the mMSS, body temperature, and IL-6 data indicate that the described model of endotoxemia induced an acute systemic hyperinflammatory response immediately after the first LPS injection, reaching a peak after the third dose and resolving at nearly 72 h after the last injection." (PMID 39266325, 2024). "In horses with experimental endotoxemia, pentoxifylline lowers thromboxane B2 concentrations, respiratory rate and rectal temperature, and, when combined with flunixin meglumine, lower WBCs and higher interleukin-6 concentrations." (PMID 39565809, 2024).
endotoxemia (continued). "Several inflammatory mediators, derived from the host cells, are responsible for most manifestations of endotoxemia, causing an increase in the production of endogenous cytokines, such as TNF-α and IL-6, IL-8, and IL-10, which play a critical role in inflammatory responses." (PMID 38338117, 2024). "Postprandial serum IL-6 increased similarly after test meals, but RO provoked a greater increase in postprandial concentrations of glycoprotein acetyls (GlycA), as well as 8 h sCD14, an endotoxemia marker." (PMID 38380649, 2024). "In contrast, the increase in TNF-α, which stimulates the subsequent IL-6 release in response to endotoxemia, is restrained by the splanchnic nerves that provide neural control to abdominal organs including the spleen and involves non-β2- adrenoreceptor mechanisms." (PMID 37535121, 2023). "Thus, the endotoxemia-related macrophageal production of IL-6 (to recruit and engage other cells) and IL-8 (a response to endotoxemia-related defense and increased oxidative stress) can be initiated." (PMID 37840804, 2023). "Alcohol addiction can lead to endotoxemia and the increased secretion of pro-inflammatory cytokines, like interleukin-1β (IL-1β) and interleukin-6 (IL-6), which can alter various signaling pathways and cause damage in the central nervous system and other organs." (PMID 38275640, 2023). "Further, contact of blood components with the surface of the extracorporeal circuits, reperfusion injuries, endotoxemia, and surgical trauma are among the processes that can activate the pro-inflammatory system and cytokine release, mainly interleukin-6 (IL-6) during on-pump CABG." (PMID 37803334, 2023). "Cholinergic anti-inflammatory pathways are potently activated by electrical VNS, as demonstrated in previous studies that prevented the release of pro-inflammatory cytokines such as TNF-⍺, IL-1β, IL-6, and IL-18 during endotoxemia, and in patients receiving tragus stimulus following acute MI." (PMID 37801130, 2023). "IL-6 plays a key anti-inflammatory role in acute phase inflammatory response and has been found to exert critical control over proinflammatory cytokines in models of endotoxic lung and endotoxemia." (PMID 36322182, 2023). "Following LPS infusion to horses, there was also an increase in circulating IL-6, and an increase in systemic and peritoneal IL-6 has been associated with strangulating or inflammatory intestinal disorders, endotoxemia, and non-survival." (PMID 37238029, 2023). "Therefore, we investigated the effect of terrein on the serum levels of IL-1β and IL-6 in an LPS-induced endotoxemia model." (PMID 36422559, 2022). "However, in another study of experimental mice endotoxemia, mTH was related to a significant increase of both plasma IL-10 and IL-6." (PMID 36012493, 2022). "As TNF-α can modulate endotoxin-induced upregulation of IL-1β and IL-6, we thus conjectured that the SEM18 peptide can decrease the endotoxemia-induced upregulation of IL-1β and IL-6 in plasma and lung tissues as well as the endotoxemia-induced bindings of IL-1β/IL-1R and IL-6/IL-6R in lung tissues." (PMID 35337084, 2022). "Additionally, LPS administration in splenectomy mice induced lower serum cytokines (TNF-α and IL-6) than LPS-administered sham mice, perhaps due to LPS tolerance from pre-existing post-splenectomy endotoxemia." (PMID 35163596, 2022). "To investigate whether the protective effect of terrein on LPS-induced endotoxemia is mediated by inhibiting inflammatory responses, we analyzed the serum levels of inflammatory cytokines, including IL-1β and IL-6." (PMID 36422559, 2022). "In addition, animals resuscitated with PolyHSA had significantly lower serum IL-6 levels compared to animals treated with HSA 6 h after LPS induced endotoxemia." (PMID 34035380, 2021).
endotoxemia (continued). "In the present study, the PLA data indicated that KCF18 could simultaneously inhibit more than 70% binding of TNF-α to TNFR1, more than 80% binding of IL-1β to IL-1R, and approximately 70% binding of IL-6 to IL-6R in the liver tissues of mice with endotoxemia." (PMID 34065201, 2021). "LPS-stimulated endotoxemia is mediated by Toll-like receptor-4 (TLR-4), which causes overwhelming production of tissue-damaging cytokines tumor necrosis factor-α (TNF-α), interleukin-1 (IL-1), and interleukin-6 (IL-6) and free radicals." (PMID 33875135, 2021). "In this study, we evaluated the presence of early markers of cardiovascular risk represented by interleukine-6 (IL-6), Intercellular Adhesion Molecules (ICAM) and endotoxemia and their correlation with metabolic markers of IR represented by insulinemia, HOMA index and plasma cortisol." (PMID 33924229, 2021). "The pooled DORs of endotoxemia were 3.2 and 5.8 in association with GNBSIs with Escherichia coli and those with Pseudomonas aeruginosa, which were both lower than the DORs of PCT, CRP, and IL-6 derived in our study." (PMID 32076461, 2020). "The authors then experimentally showed that CGP-60474 alleviated tumor necrosis factor-α (TNF-α) and interleukin-6 (IL-6) levels in activated macrophages, downregulated the NF-κB activity, and reduced the mortality rate in lipopolysaccharide induced endotoxemia mice." (PMID 32934806, 2020). "In addition, the serum levels of TNF-α and IL-6 in TEPP-46-pretreated mice were significantly decreased compared to those in endotoxemia mice." (PMID 33542713, 2020). "The important aspect of assessing non-lethal endotoxemia was that the administration of SM caused an increase in the serum level of IL-6." (PMID 33114200, 2020). "IL-6 is a pleiotropic cytokine that is commonly produced at local tissue sites and released into circulation in almost all situations of homeostatic perturbation typically including endotoxemia, endotoxic lung, trauma and acute infections." (PMID 31482249, 2019). "Indeed, in one case study of a patient with acute endotoxemia, ibuprofen was actually found to cause significant increases of circulating pro-inflammatory TNF-α and IL-6." (PMID 30400801, 2018). "Furthermore, leptin pre-treatment decreased the oxidative stress burst in blood and blunted the increased pro-inflammatory cytokines TNF-α, IL-1β, and IL-6 observed during endotoxemia." (PMID 30618812, 2018). "Notably, the intestinal hyper-permeability was associated with portal endotoxemia and increased hepatic/MAT/intestinal macrophage infiltration, inflammation and corresponding cytokines levels (IL-6, MCP-1, F4/80, TNFα, NFκBp65, TNFRI and TLR4) in NASH-V rats." (PMID 29684027, 2018). "However, vehicle-treated/endotoxemic rats showed strong increased TNF-α, IL-1β, and IL-6 levels, indicating that a severe inflammatory response was evoked by endotoxemia (respectively)." (PMID 30618812, 2018). "Furthermore, leptin treatment decreased the oxidative stress burst in the blood and blunted the increased pro-inflammatory cytokines TNF-α, IL-1β, and IL-6 observed during endotoxemia." (PMID 30618812, 2018). "Furthermore, leptin treatment decreased the oxidative stress burst in blood and blunted the increase in pro-inflammatory cytokines TNF-α, IL-1β, and IL-6 observed during endotoxemia." (PMID 30618812, 2018). "Cytokine IL-6 is released following trauma, endotoxemia and organ injury." (PMID 28670523, 2017). "Interestingly, RIPC was shown to down-regulate the serum levels of TNF-α and IL-6 in a rat model of lipopolysaccharide-induced endotoxemia, suggesting that its protective effects were at least in part due to its direct suppression of pro-inflammatory pathways." (PMID 29232398, 2017). "Furthermore, the capability of the mutated peptides to block LPS-dependent TNF-α and IL-6 secretion by mouse RAW 264.7 macrophages in vitro, as well as mice displaying endotoxemia mice in vivo were also investigated." (PMID 28054660, 2017).
endotoxemia (continued). "Compared with serum PCT, IL-1β and IL-6, CitH3 is more responsive to endotoxemia." (PMID 28827548, 2017). "Ex vivo stimulation of monocytes with LPS, C. albicans, or S. aureus demonstrates clear immunosuppression at 4 h after LPS administration, illustrated by significant attenuation of IL-1β and IL-6 production following endotoxemia, compared with the placebo group." (PMID 29312282, 2017). "The sustained higher levels of cytokines IL-6 and IL-10 at the later hours could be partially responsible for imparting a protective role in endotoxemia." (PMID 25759837, 2015). "Subsequently, a body of animal and clinical trials reported that dexmedetomodine reduced the level of plasma cytokines, including TNF-α, IL-1 and IL-6, stimulated by endotoxemia, and that dexmedetomidine reduced the mortality rate in endotoxemia-induced shock rat models in a dose-dependent manner." (PMID 24345905, 2014). "However, several investigations demonstrated the impact of perioperative endotoxemia and subsequent activation of acute-phase mediators, such as IL-6 and CRP, in patients with intestinal, general, vascular and heart surgery." (PMID 24266958, 2013). "Endotoxemia represents a trigger of acute-phase reaction proteins such as IL-6 and CRP." (PMID 24266958, 2013). "However, this is not likely, given the consistent findings in animal studies and isolated cell studies and given the observation that administration of exogenous adenosine can limit the IL-6 response during human experimental endotoxemia." (PMID 21211004, 2011). "In addition, the sex, age, feeding, and housing of the cattle, which varied between studies, may have had an effect on how they coped with endotoxemia, and therefore also IL-6 and cortisol levels." (PMID 38807585, 2024). "Moreover, dobutamine treatment already showed its anti-inflammatory effects through TNF-α and IL-6 reduction in rats with endotoxemia and in septic shock patients; however, in this study, for the first time, we demonstrated that this reduction is associated with NF-κB downregulation." (PMID 38790971, 2024). "Since prostaglandins have been shown to affect the formation of pro-inflammatory cytokines, such as IL-6, and IL-1β has been shown to induce mRNA expression of COX-2, COX-inhibitors remain central to the treatment of the profound systemic inflammatory response associated with endotoxemia." (PMID 37238029, 2023). "In contrast to the stimulatory effects of IL-6 on leptin, physiologic-range hyperleptinemia has been shown to attenuate the IL-6 response to endotoxemia, suggesting cord blood IL-6 levels could be attenuated in large for gestational age infants that are characteristically hyperleptinemic." (PMID 35197933, 2022). "KCF18 could effectively decrease the p65 nucleus translocation induced by cytokines, and a mice endotoxemia experiment demonstrated that KCF18 could reduce the expression of IL-6 and the increase of white blood cells in the blood stimulated by lipopolysaccharides." (PMID 35370629, 2022). "Likewise, BAM15 also attenuated other parameters of systemic inflammation, as indicated by serum cytokines (TNF-α, IL-6, and IL-10) and serum cell-free DNA (cf-DNA), which might be due to the reduction in endotoxemia and bacteremia." (PMID 35628259, 2022). "Inhalation of hydrogen gas significantly increased the survival rate of endotoxemia mice, and improved lung injury and lung function, such as lung injury scores, pulmonary edema and hemorrhage, neutrophil infiltration, IL-6 secretion, and the blood flow velocity of the pulmonary circulation." (PMID 33767697, 2021). "Considering that TNF-α, IL-1β, and IL-6 as well as their bindings to the cognate receptors play crucial roles in mediating the development of endotoxemia-induced organ injury, we hypothesized that KCF18 can alleviate acute liver injury in mice with endotoxemia." (PMID 34065201, 2021).
endotoxemia (continued). "Also, it seems that the increase of these miRNAs at 24 h may be part of a rapid response to oxidative stress and endotoxemia induced by sleep deprivation processes that foster the secretion of proinflammatory cytokines, as in the case of IL-6." (PMID 30225174, 2018). "The results of this study demonstrate that the suppression of cardiac vagal activity and sympathetic predominance during endotoxemia are predominantly linked to the anti-inflammatory IL-1ra response to IL-1ß activation rather than to the pro-inflammatory response by IL-6 or TNF-α." (PMID 25893426, 2015). "Thus, blocking TLR-4 or administering IL-6 or IL-10 might impart protection against endotoxemia in the clinical field." (PMID 25759837, 2015). "Anti-inflammatory finding agrees with previous work that showed ertugliflozin significantly decreased IL-6 and TNF-a levels in mice exposed to endotoxemia." (PMID 41341617, 2025). "In females, PDK4 overexpression primarily increased IL-6 expression and significantly elevated MPO levels during endotoxemia compared with WT females." (PMID 40626362, 2025). "It resulted in the reduction of endotoxemia (through LPSs) and pro-inflammatory cytokine (TNF-α, IL-6, and IL-1β) levels, with the increased expression of tight-junction associated proteins (claudin-1, occludin, and zonula occludens-1)." (PMID 41334341, 2025). "Several studies have shown that L. lactis can attenuate LPS-induced endotoxemia by reducing proinflammatory cytokines such as TNF-α and IL-6, preserving intestinal integrity, and limiting microbial translocation." (PMID 40964057, 2025). "To study the effects of capsaicin on endotoxemia and systemic inflammation, we measured serum levels of LPS, TNF-α, and IL-6." (PMID 39201665, 2024). "For example, a recombinant 53 kDa glycoprotein from TsES (rTsP53) displays anti-inflammatory characteristics and protects mice from endotoxemia induced by lipopolysaccharides (LPS) by reducing levels of pro-inflammatory agents (TNF-α, IL-1β, and IL-6)." (PMID 38727220, 2024). "Particularly, after endotoxemia, animals with obstructive jaundice often exhibit more intense systemic and pulmonary production of TNF-α and IL-6, as well as increased accumulation and activation of inflammatory cells." (PMID 39744639, 2024). "We observed that increased circulating levels of LBP, a marker of metabolic endotoxemia in parallel with elevated CRP, leptin, and IL-6 levels, and decreased adiponectin levels were found in overweight women." (PMID 37841878, 2023). "The results demonstrated that LPS-induced endotoxemia increased GOLPH3 expression, followed by the induction of Golgi stress and excessive pro-inflammatory mediators (Tnfα, IL-6, and IL-1β) in mice." (PMID 37479687, 2023). "The significant elevation of plasma LPS, IL-6, and MCP1 in wild-type mice indicated that CRS induces endotoxemia and systemic inflammation." (PMID 36817471, 2023). "We found that F-652 injection significantly improved the survival rates and reduced pro-inflammatory cytokines (IL-6, TNF-a, IL-1β, MCP-1) in LPS-induced endotoxemia mice." (PMID 36123595, 2022). "This indicated that KCF18 alleviated the mRNA expression levels of the inflammatory cytokines TNF-α, IL-1β, IL-6, and MCP-1 in an endotoxemia mouse model with liver injury." (PMID 35370629, 2022). "Baicalein decreased the generation of TNF-α or IL-6 and inhibited the activation of NF-κB or ERK1/2 in mice with LPS-induced lethal endotoxemia." (PMID 33995078, 2021). "As detected, high levels of pro-inflammation cytokines IL6, IL1β and IL18 in endotoxemia colon were reversed by JQ1 pretreatment." (PMID 33679744, 2021). "Since endotoxemia is an infection-induced systemic inflammatory response, the expressions of pro-inflammatory factors IL6, IL18, and IL1β in endotoxemia colon were calculated by Q-PCR and western blot." (PMID 33679744, 2021).